FAM182A (family with sequence similarity 182 member A)
Synonyms: bB329D4.1; C20orf91A; C20orf91
Gene: Long non-coding RNA gene on chromosome 20 (25,985,095 to 26,100,347, forward strand). Ensembl gene ENSG00000125804.
Diseases named in the same sentence as FAM182A in open-access papers:
FAM182A is named in the same sentence as 1 disease in open-access papers, as found by Europe PMC text mining. Sharing a sentence is not in itself a finding about the gene and the disease. The quoted sentences say what the papers report.
cancer (1 paper, 2022). A tumor composed of atypical neoplastic, often pleomorphic cells that invade other tissues. "Genes such FAM182A, SOX9, AHNAK2, ENSG00000121031, FLT3LG, PMEPA1, ZFP36L2 in the large intestine, ALB, KRTAP19-1, APOB, CD200, CRYGD, KRTAP24-1, OR6N2 in the liver are novel predictions, and their functions in these cancers can further be studied." (PMID 34997044, 2022).